PCSK1 (proprotein convertase subtilisin/kexin type 1)
Diseases named in the same sentence as PCSK1 in open-access papers (continued):
Sharing a sentence is not in itself a finding about the gene and the disease.
Obesity (continued). "Some in vitro studies showed that chemical chaperones and a newly FDA-approved drug, Setmelanotide (an MC4R agonist), could be used to treat some monogenic forms of obesity due to POMC, PCSK1, or LEPR deficiency." (PMID 38003551, 2023). "A study conducted on Danish subjects analyzed 3074 obese and 2790 non-obese subjects and found associations between PCSK1 rs6232 and rs6235 and obesity." (PMID 37761915, 2023). "In 2020, the Food and Drug Administration (FDA) approved the first treatment involving the MC4R agonist setmelanotide for chronic weight management in adult and pediatric patients at least 6 years of age with obesity due to three rare genetic conditions: POMC, LEPR, or PCSK1 deficiency." (PMID 37571382, 2023). "In addition, the G allele of PCSK1 SNP rs6235 was individually associated with obesity and metabolic syndrome, and the G allele of PPARG rs1801282 was associated with obesity." (PMID 37761915, 2023). "We appreciate that heterozygous mutations in genes such as ALMS1, BBSs, LEPR, POMC, and PCSK1 have not been shown to be sufficient to cause the disease of obesity, except for the complete loss-of-function mutations of PCSK1, but not for POMC or LEPR mutations." (PMID 37835041, 2023). "In addition, the PCSK1 rs6235 G allele was associated with obesity and metabolic syndrome, and the PPARG1 rs3856806 T allele was associated with obesity." (PMID 37761915, 2023). "Furthermore, we found life-long Pcsk1 knockout in POMC neurons to induce obesity which resolved after 6 and 12 months of age in male and female mice, respectively." (PMID 35963866, 2022). "Several different studies with restricted cohort sizes have also looked at the association between rare heterozygous coding PCSK1 variants and obesity without positive results." (PMID 36292633, 2022). "In conclusion, we suggest that the PCSK1 p.Y181H variant is a founder variant which does not contribute to an increased obesity risk." (PMID 36292633, 2022). "Low PCSK1 expression might be related to obesity and diabetes, and PPARGC1A expression can increase obesity risk." (PMID 35328013, 2022). "Notwithstanding these reports on absent or restricted association between rare heterozygous PCSK1 variants and obesity, recent studies with extensive cohorts do make a compelling case for their relevance." (PMID 36292633, 2022). "Despite the evident influence of PCSK1 on obesity and the known functions of other PCSKs in lipid metabolism, the role of PCSK1 specifically in lipid and cholesterol metabolism remains unclear." (PMID 34996527, 2022). "The homozygous PCSK1 variant is suggested to be the cause of their obesity, although none of their three siblings or parents, who carry the same PCSK1 variant in a heterozygous state, are obese (BMI = 25–27 kg/m2)." (PMID 36292633, 2022). "Thus, Pcsk1 ablation in early adulthood in rodents phenocopies hyperphagic obesity as seen in human PC1/3-obesity." (PMID 35963866, 2022). "The arcuate nucleus was found to be the region most enriched by the 9 known human monogenic obesity genes, with the highest expression of Pomc, Pcsk1, and Lepr genes, followed by the embryonic hypothalamus, with prevalent expression of Sim1, Pomc, and Tub genes." (PMID 34283813, 2021). "Setmelanotide is prescribed for the treatment of rare genetic diseases of obesity caused by certain variants of the genes encoding for pro-opiomelanocortin (POMC), proprotein convertase subtilisin/kexin type 1 (PCSK1), or leptin receptor (LEPR) all of which cause a deficiency of these molecules." (PMID 33670364, 2021). "Because alterations of Pcsk1 gene expression have been reported in relation to many diseases, such as diabetes mellitus, obesity, Alzheimer's disease, Huntington's disease and Prader–Willi syndrome, it is important to understand the basic mechanisms responsible for its regulation." (PMID 32319174, 2020).
Obesity (continued). "Some of the genes associated with monogenetic severe obesity are: leptin (LEP), leptin receptor (LEPR), proopiomelanocortin (POMC), MC4R, preproconvertase 1 (PCSK1), single minded 1 (SIM1), brain-derived neurotrophic factor (BDNF), and tyrosine kinase receptor tropomycin-related kinase B (TrkB)." (PMID 32982666, 2020). "However, the mutation rates of five obesity-related genes in few cancer tissues were >0.05 (i.e., LEPR in SKCM (0.11), UCEC (0.07), and LUSC (0.07) and PCSK1 in SKCM (0.09) and UCEC (0.06))." (PMID 33299884, 2020). "Candidate obesity genes and traits associated with obesity include LEP, MCR4, POMC, and PCSK1." (PMID 33113859, 2020). "In addition to early-onset obesity and hyperphagia, subjects with PWS and those with PCSK1 deficiency have other common clinical characteristics." (PMID 29880780, 2018). "Therefore, bariatric surgery can be considered when treating severe obesity in patients with PWS and PCSK1 deficiency." (PMID 29880780, 2018). "They report that such neurons, with deletions encompassing Snord116, show reduced expression of PCSK1 (encoding prohormone covertase), which has been previously implicated in human obesity, and a transcription factor NHLH2, which regulates expression of the PCSK1 gene." (PMID 29376887, 2018). "When further adjusted for BMI, the obesity predisposing loci, GNPDA2-rs16858082 (P = 0.016) and PCSK1-rs261967 (P = 0.026) were still nominally associated with total cholesterol (TC) levels, and MC4R-rs2331841 remained correlated with fasting glucose (FBG) levels (P = 0.012)." (PMID 29212175, 2017). "Partial loss of function heterozygous mutations in PCSK1 present a non-fully penetrant intermediate obesity phenotype However, heterozygous carriers of a null mutation show a dominantly inherited form of Mendelian obesity." (PMID 25825681, 2015). "Our results suggest that further study of less common and rare variations in PCSK1 from both biochemical and genetic standpoints will be useful in elucidating the mechanisms by which variant PC1/3s contribute to metabolic diseases such as obesity and diabetes." (PMID 23383060, 2013). "While the PC1/3 null mouse is not obese, a mouse model of obesity has been generated via introduction of a missense mutation in PCSK1 at amino acid position 222, near the calcium-binding pocket in the catalytic domain." (PMID 23383060, 2013). "In addition, four independent genome-wide linkage studies for obesity-related traits delineate a common 5.6-Mb interval on chromosome 5q where PCSK1 resides." (PMID 22043164, 2011). "A subsequent study in 3,885 non-diabetic Swedes failed to confirm the association between the PCSK1 rs6235 and obesity." (PMID 20498726, 2010). "Among other genes, this locus harbors PCSK1, and associations of two common single nucleotide polymorphisms (SNPs) within this gene (rs6232 and rs6235, minor allele frequency (MAF) = 5.4% and 27.3%, respectively) with obesity were reported." (PMID 20534142, 2010). "Case-control analyses of PCSK1 rs6234 with obesity and overweight." (PMID 20498726, 2010). "In this population-based sample of Chinese Hans, we did not replicate the association between the PCSK1 rs6234-rs6235 pair and obesity risk previously reported by original study in European populations." (PMID 20498726, 2010). "Quantitative traits analyses of PCSK1 rs6234 with obesity related traits." (PMID 20498726, 2010). "Setmelanotide has also been approved for the treatment of obesity and hunger due to genetic disorders such as Bardet-Biedl syndrome, pro-opiomelanocortin (POMC) loss-of-function, including proprotein convertase subtilisin/kexin type 1 (PCSK1), and LEPR deficiency." (PMID 40297673, 2025). "In addition, setmelanotide is pioneering a personalized medicine approach to obesity, specifically targeting very rare genetic disorders such as pro-opiomelanocortin (POMC) deficiency, proprotein convertase subtilisin/kexin type 1 (PCSK1) deficiency, and leptin receptor deficiency." (PMID 40016558, 2025).
Obesity (continued). "Notably, Pcsk1 and Hmox1 play important roles in preventing obesity and metabolic disease." (PMID 37770553, 2023). "The most frequent causes of monogenic obesity are mutations in the genes leptin (LEP), leptin receptor (LEPR), melanocortin 4 receptor (MC4R), proopiomelanocortin (POMC), proprotein convertase subtilisin/kexin type 1 (PCSK1), and neurotrophic receptor tyrosine kinase 2 (NTRK2)." (PMID 37375898, 2023). "In addition to adipokines, increased expression of genes such as Pcsk1 and Hmox1, which play important roles in preventing obesity and metabolic disease, could potentially contribute to reducing the risk of metabolic disease post slurry treatment." (PMID 37770553, 2023). "Furthermore, recent meta-analyses have only indicated a robust association for scarce disruptive heterozygous PCSK1 variants with obesity, while clinical significance is less or sometimes lacking for most nonsynonymous variants." (PMID 36292633, 2022). "Further causing doubt into the hypothesis that rare heterozygous PCSK1 variants can singlehandedly cause obesity is the general lack of reports on obesity from first-degree relatives of patients with PC1/3 deficiency." (PMID 36292633, 2022). "Notably, other loci such as MC4R, PCSK1, and BDNF, are well known to be associated with severe early-onset obesity and harbor genes involved in the regulation of leptin-melanocortin pathways in the hypothalamus, thus are thought to affect body weight largely through impacting appetite." (PMID 31285522, 2019). "For other cardiometabolic traits, the obesity predisposing locus, FTO-rs1558902 yielded significant association with systolic blood pressure (SBP) (P = 0.001), while the risk alleles of SNPs in/near GNPDA2, PCSK1 and MAP2K5 yielded nominal association with blood pressures (P < 0.05)." (PMID 29212175, 2017). "Thus, common variation at PCSK1 gene is not an essential contributor to the risk of obesity in multi-ethnic American population." (PMID 23451278, 2013). "To determine whether rs6232 and rs6235 PCSK1 polymorphisms contribute to obesity in the MESA cohort, we performed association analyses with BMI variation and obesity risk in each ethnic group (European-Americans, African-Americans, Asians and Hispanics) of the MESA cohort." (PMID 23451278, 2013). "Interestingly, we found that the PCSK1 rs6234 risk G-allele was marginally associated with obesity and significantly associated with combined obesity/overweight in men, but not in women when the analyses were stratified by gender." (PMID 20498726, 2010). "In our cohort, the reported association of the common variants rs6232 and rs6235 within the PCSK1 gene with BMI and obesity could not be replicated." (PMID 20534142, 2010). "This contrasts with homozygous/bi-allelic carriers of LoF mutations in other genes in the leptin-melanocortin signalling pathway -LEP, LEPR, POMC, PCSK1 and MC4R-who almost inevitably develop severe obesity at an early age." (PMID 41386534, 2026). "Apart from the well-known obesity genes (LEP, PCSK1, NTRK2), we identified several BMI effector genes that have not been reported in GWAS but are supported by multiple converging lines of evidence." (PMID 38167462, 2024). "A significant inverse correlation between birth weight and obesity and diabetes genes, including MTNR1B, NTRK2, PCSK1, and PTEN genes (r= -0.221, -0.235, -0.246, and − 0.418, respectively)." (PMID 36997916, 2023). "The current study found a significant inverse correlation between birth weight and obesity and diabetes genes, including MTNR1B, NTRK2, PCSK1, and PTEN (r= -0.221, -0.235, -0.246, and − 0.418, respectively)." (PMID 36997916, 2023). "We examined dry mass, wet mass, triglyceride levels, and survival during starvation in these 4 lines and found that PCSK1 showed a consistent ‘obesity’ phenotype, in accord with the involvement of PCSK in human monogenic obesity." (PMID 33242659, 2021).
Obesity (continued). "Compared to the normal tissues, five obesity-related genes (POMC, LEP, PCSK1, MTCH2, and GPR120) did show a similarity alteration of DNA methylation patterns in different cancer tissues." (PMID 33299884, 2020). "The expression levels of other eight obesity-related genes (TMEM18, KCTD15, GNPDA2, SH2B1, FTO, LEP, PCSK1, and GPR120) in about half types of cancer tissues were higher/lower than those in the corresponding normal tissues." (PMID 33299884, 2020). "Compared to the normal tissues, the five obesity-related genes (POMC, LEP, PCSK1, MTCH2, and GPR120) showed a similarity alteration of DNA methylation patterns in different cancer tissues." (PMID 33299884, 2020). "Six novel variants were identified in five candidate genes in seven out of 105 children with severe obesity; two in SIM1 (p.W306C and p.Q36X), one in POMC (p.Y160H), one in PCSK1 (p.W130G fs Ter8), two in MC4R (p.D126E) and one in LEPR (p.Q4H)." (PMID 30991789, 2019). "Some of the monogenic obesity genes which manifest as severe obesity in children are leptin (LEP), leptin receptor (LEPR), pro-opiomelanocortin (POMC), and prohormone convertase 1 (PCSK1)." (PMID 28924523, 2017). "In summary, in our sample of Chinese children, we replicated eight adult East Asian obesity-related loci (in/near FTO, MC4R, GNPDA2, PCSK1, SEC16B, MAP2K5, ITIH4 and BDNF) in the same direction of effect as previous reports in adults." (PMID 29212175, 2017). "Notably, rare, pathogenic mutations in all the genes involved in leptin driven melanocortin pathway (LEP, LEPR, POMC, PCSK1, MC4R, primarily) lead to severe early-onset obesity accompanied by eating disorders." (PMID 39237720, 2025). "In contrast, pancreatic β cell-specific Pcsk1 ablation leads to profound hyperphagic obesity mediated by the lack of mature insulin." (PMID 35963866, 2022). "Significant differences were found in the number of carriers with and without obesity for the PCSK1 gene [p=0.031 (0.011-0.118)], [BMI SDS=2.6 (0.7)]." (PMID 35574020, 2022). "The results in mice are mixed, since homozygous Pcsk1 knock-out mice do not develop obesity but dwarfism." (PMID 35955861, 2022). "Both Nhlh2-null and Pcsk1-hypomorphic mouse models recapitulate core aspects of the PWS symptomatology, such as an impaired hypothalamic axis, growth retardation and eventually obesity." (PMID 35955861, 2022). "An agonist of the MC4R, used in individuals with severe obesity due to either POMC, PCSK1, or LEPR deficiency, and should not be used for other types of obesity such as general obesity." (PMID 34552557, 2021). "Among these, only survival probability of KIRC patients could be impacted by gender and expression levels of four obesity-elated genes (LEP, MC4R, TMEM18, and PCSK1)." (PMID 33299884, 2020). "Although the mechanism of most genetic loci predispose individuals to obesity is not clear so far, evidence indicated that they were involved in energy uptake (FTO, MC4R, PCSK1, and BDNF) and adipocyte differentiation (FTO, TMEM18, BDNF, MTCH2 and NEGR1)." (PMID 24626232, 2014). "For instance, like fellow genes associated with earlier age at onset of obesity such as MC4R and PCSK1, SLTM may affect neurohormonal pathways that were not directly tested by our functional assay." (PMID 40912257, 2025). "We next built a prioritization score that weighs each of the eight methods based on whether or not they prioritized one or more of the six established obesity genes located in any of the 536 BMI-associated loci (i.e., LEPR, POMC, PCSK1, DGKI, SH2B1, and MC4R)." (PMID 38754426, 2024). "However, it is not approved for treating obesity in individuals not impacted by POMC, PCSK1, LEPR deficiency, or Bardet-Biedl syndrome." (PMID 37937009, 2023).
Obesity (continued). "Genes encoding leptin (LEP), leptin receptor (LEPR), melanocortin 4 receptor (MC4R), proprotein convertase subtilisin/kexin type 1 (PCSK1), proopiomelanocortin (POMC), kinase suppressor of ras 2 (KSR2), adenylate cyclase 3 (ADCY3), and others contribute to the development and progression of obesity." (PMID 36141228, 2022). "Although diverse anti-obesity drugs are currently approved for the treatment of obesity (orlistat, naltrexone/bupropion, and liraglutide 3.0 mg), none has been specifically studied in patients with PWS or PCSK1 deficiency." (PMID 29880780, 2018). "In this study, we found modest evidence for association of the PCSK1 rs6234 with BMI and overweight in men only but not in women, which suggested that PCSK1 rs6234 might not be an important contributor to obesity in Chinese Hans." (PMID 20498726, 2010). "Besides SIM1 and MC4R, the haploinsufficiency of proprotein convertase 1 (PCSK1), melanocortin 2 receptor accessory protein 2 (MRAP2) in the brain, iroquois homeobox 3 (IRX3) in fat or uncoupling protein 3 (UCP3) in mitochondria are also responsible for human obesity." (PMID 31124015, 2019).
Bardet-Biedl syndrome (18 papers, 2019 to 2025). A ciliopathy with multisystem involvement. "Rare MC4R pathway diseases of obesity include proopiomelanocortin, proprotein convertase subtilisin/kexin type 1, or leptin receptor deficiency, or Bardet-Biedl syndrome (BBS)." (PMID 40847358, 2025). "Although multiple melanocortin receptor agonists have been investigated, setmelanotide is currently the only MC4R agonist approved by the FDA for the treatment of specific genetic forms of obesity, including deficiencies in POMC, PCSK1, and LepR, as well as Bardet-Biedl syndrome (BBS)." (PMID 41016636, 2025). "Informed by these mechanistic studies, successful phase 3 clinical trials have led to a second generation MC4R agonist being licensed in many countries for the treatment of several monogenic disorders (POMC, PCSK1, LEPR deficiencies and Bardet-Biedl Syndrome (BBS))." (PMID 37661743, 2023). "It is indicated for patients aged ≥2 years with obesity due to proopiomelanocortin (POMC), PCSK1, leptin receptor (LEPR) deficiencies, or Bardet-Biedl syndrome (BBS), with dosing adjusted by age and weight." (PMID 41393538, 2025). "POMC, PCSK1, and LEPR deficiencies and Bardet-Biedl syndrome (BBS) can be counter-regulated by the MC4R agonist setmelanotide." (PMID 40822950, 2025).
diabetes (15 papers, 2013 to 2026). "MiR‐197‐3p can regulate glucose metabolism by suppressing PCSK1/3 to inhibit GIP and GLP‐1 production, incretin hormones implicated in the pathogenesis of diabetes." (PMID 34984856, 2022). "This revealed high IP activity in the field of PCSKs, with patents ranging from biomarkers of diabetes (PCSK1 and PCSK2), to biomarkers and drug targets in cancer (FURIN and PCSK6), with the highest number of patents expectedly related to PCSK9." (PMID 36188622, 2022). "Interestingly, at least 12 genes including SLC2A2, G6PC2, SLC30A8, PCSK1 and RAPGEF4, also overlap with previously implicated genes from genome wide association studies (GWAS) for type 2 diabetes mellitus and blood glucose loci." (PMID 31682591, 2020).
Sepsis (11 papers, 2019 to 2025). Sepsis is defined as life-threatening organ dysfunction caused by a dysregulated host response to infection. "Since the detrimental pro-inflammatory phenotype of Pcsk1 global knockout mice was not reproducible in immune cell-specific Pcsk1 knockout mice, we reasoned that there must be another anti-inflammatory PC1/3-cleaved peptide that modulates sepsis susceptibility." (PMID 39435302, 2024).
colitis (9 papers, 2019 to 2024). Inflammation of the colon. "The patient harboring the PCSK1 variant was of Asian ancestry and presented with indeterminate mild colitis before the age of one when recruited to the study." (PMID 32081864, 2020).